TNMD (tenomodulin)
Description:
May be an angiogenesis inhibitor.
Synonyms: TeM; ChM1L; myodulin; tendin; BRICD4
Tractability: Antibody: UniProt predicts a signal peptide or a membrane-spanning region.
Gene: Protein-coding gene on chromosome X (100,584,936 to 100,599,885, forward strand). Ensembl gene ENSG00000000005.
Subcellular location: Membrane (Isoform 1); Nucleus envelope; Membrane (Isoform 2); Cytoplasm (Isoform 3)
Gene Ontology:
Molecular function: protein binding
Biological process: negative regulation of angiogenesis; negative regulation of endothelial cell proliferation
Cellular component: cytoplasm; membrane; nuclear envelope
Homologues: Orthologues: chimpanzee TNMD (99% identical), macaque TNMD (99% identical), pig TNMD (98% identical), rabbit TNMD (98% identical), dog TNMD (97% identical), mouse Tnmd (96% identical), rat Tnmd (94% identical), guinea pig TNMD (78% identical), tropical clawed frog tnmd (54% identical), zebrafish tnmd (42% identical). Paralogues in human: CNMD (34% identical).
Diseases named in the same sentence as TNMD in open-access papers:
TNMD is named in the same sentence as 12 diseases in open-access papers, as found by Europe PMC text mining. Sharing a sentence is not in itself a finding about the gene and the disease. The quoted sentences say what the papers report.
Obesity (3 papers, 2019 to 2025). Accumulation of substantial excess body fat. "For some of the most up‐ or downregulated DEGs, namely NQOI, GPD1L, and TNMD, the link to obesity, weight loss, or diabetes mellitus is described." (PMID 40229590, 2025). "Several sex-dependent associations have been observed between single-nucleotide polymorphisms (SNPs) of the TNMD gene, which is located in the X-chromosome, and obesity, type 2 diabetes mellitus (T2DM), and metabolic syndrome in adults." (PMID 30850679, 2019). "Tenomodulin (TNMD) is a type II transmembrane glycoprotein that has been recently linked to obesity, and it is highly expressed in obese adipose tissue." (PMID 30850679, 2019). "Although EGR1 and TNMD genes share the same expression profile in white adipose tissues of obese patients, in contrast to EGR1, TNMD acts as a protective factor in visceral adipose tissue to alleviate insulin resistance in obesity." (PMID 32121305, 2020). "Associations in line with this result have been previously identified in adult females in relation to TNMD haploblock-1 SNPs21, which suggests that TNMD could mediate its putative effects on obesity via low-grade inflammation." (PMID 30850679, 2019). "The TNMD gene is primarily expressed in SAT of subjects with obesity as compared to subjects without obesity." (PMID 40229590, 2025). "CD248, which has been recently linked with insulin metabolism, NAD(P)H quinone dehydrogenase 1 (NQO1) and tenomodulin (TNMD) were downregulated following LIWL, and expression was reduced in SAT of individuals with or without obesity of the LATC and OA cohorts." (PMID 40229590, 2025). "CD248, which has been recently linked with insulin metabolism, NAD(P)H quinone dehydrogenase 1 (NQO1) and tenomodulin (TNMD) were downregulated following LIWL, and their expression was also reduced in SAT of individuals with or without obesity of the LATC and OA cohort." (PMID 40229590, 2025).
tendinopathy (3 papers, 2017 to 2019). "The images showed that most of the cultured cells from healthy samples and tendinopathy samples expressed the surface marker for vimentin (red) and tenomodulin (green), and had elongated appearances under microscopy." (PMID 28598390, 2017). "TNMD—a tendon proteoglycan responsible for collagen fiber maturation —was significantly upregulated in the chronic rupture group compared to acute ruptures and not regulated in the tendinopathy group." (PMID 29385715, 2018).
Insulin resistance (2 papers, 2016 to 2020). Increased resistance towards insulin, that is, diminished effectiveness of insulin in reducing blood glucose levels. "Here by gene silencing and generating a transgenic mouse line, we demonstrate that TNMD is required for adipocyte differentiation, and overexpression of Tnmd in adipose tissue protects mice from obesity-induced systemic insulin resistance." (PMID 26880110, 2016).
metabolic syndrome (2 papers, 2013 to 2019). A cluster of metabolic risk factors for CARDIOVASCULAR DISEASES and TYPE 2 DIABETES MELLITUS. "Interestingly, the expression of some of these genes (C1S, SAA2, ALCAM, CTSB, YKL-40 and tenomodulin) was found to be associated with some relevant metabolic syndrome features." (PMID 23975165, 2013).
type 2 diabetes (2 papers, 2017 to 2019). "Further, tendon-related markers, Scleraxis (Scx) and Tenomodulin (Tnmd) gene expression were studied in intact and healing tendons of type 2 diabetes and non-diabetic rats." (PMID 28122008, 2017).
Simpson-Golabi-Behmel syndrome (1 paper, 2019). Simpson-Golabi-Behmel syndrome is a rare X-linked multiple congenital anomalies syndrome, characterized by pre- and postnatal overgrowth, distinctive craniofacial features, variable congenital malformations, organomegaly and an increased tumor risk. "In addition, it has been demonstrated that TNMD inhibition blocks adipogenesis in Simpson-Golabi-Behmel syndrome (SGBS) preadipocytes and benefits VAT expansion in mice." (PMID 30850679, 2019).
tendinitis (1 paper, 2022). Inflammation of a tendon, usually resulting from an overuse injury. "Calebin A suppressed inflammation and exhibited potential as preventive and therapeutic treatment of tendinitis by suppressing down-regulation of tenomodulin and collagen I." (PMID 35631173, 2022).
retinopathy (1 paper, 2009). "TNMD has been reported to inhibit angiogenesis by hindering endothelial proliferation and tube formation, but this has not been confirmed in vivo since the TNMD-deficient mice did not exhibit any vascular abnormalities when examined by oxygen-induced retinopathy." (PMID 19381347, 2009).
TNMD also shares sentences with these, for which no sentence is quoted: diabetes mellitus (2 papers); age-related macular degeneration (1); cervical cancer (1); hyperglycaemia (1).